CDC42 (cell division cycle 42)
Diseases named in the same sentence as CDC42 in open-access papers (continued):
Sharing a sentence is not in itself a finding about the gene and the disease.
breast carcinoma (continued). "Different from the mechanism of Hhex regulation in breast cancer cells, our results showed that Hhex was associated with RHOA and CDC42 activation." (PMID 34321041, 2021). "Loss of RhoGDI-1 stimulates constitutive activation of Cdc42, causing increased COX-2 activity, promoting breast cancer development." (PMID 34196668, 2021). "Hyperactivation of the PAK can result from excessive activation by Cdc42/Rac1, or by upstream miRNAs, for example miR-424 was recently found to hyperactivate the cancer stem cell pool in breast cancer through activation of PAK1." (PMID 34196668, 2021). "Here, the authors report that loss of EFA6B promotes collective invasion through activation of the epithelial-to-mesenchymal transition program and CDC42-dependent signalling pathways in breast cancer." (PMID 33850160, 2021). "One study showed that diosgenin suppressed the phosphorylation of Vav2 and activation of Cdc42, leading to attenuation of cell migration of breast cancer cells, indicating that diosgenin has a therapeutic potential for metastasis therapy." (PMID 32626765, 2020). "In this review, we focused on recent exciting findings showing the effects of classical Rho GTPase (Rho, Rac and Cdc42) dysregulation on breast cancer initiation and metastasis." (PMID 32992837, 2020). "Together, these data suggest that Rac and Cdc42 activity is important for angiogenesis in breast cancer." (PMID 32992837, 2020). "We demonstrate that astrocyte uptake of breast cancer-derived EVs relies on the Cdc42-dependent clathrin-independent carrier/GPI-AP-enriched compartment (CLIC/GEEC) endocytic pathway." (PMID 32481745, 2020). "Reymond and colleagues identified Cdc42 as a critical regulator of breast cancer cell intravasation, as RNAi targeting of Cdc42 significantly inhibited the ability of MDA-MB-231 cells to migrate and invade through a layer of endothelial cells." (PMID 32992837, 2020). "Altogether, our data implicated a TKS5/FGD1/CDC42 axis in the polarization of MT1-MMP storage vesicles required for the persistent and efficient migration of breast cancer cells in a dense 3D matrix environment." (PMID 32673397, 2020). "Research has also shown that Cdc42 is integral for EGF (epidermal growth factor)-mediated cell proliferation in breast cancer." (PMID 32992837, 2020). "In support of this, it was also found that Cdc42 activation promoted the ability of breast cancer cells to close a wound and migrate in a Boyden chamber." (PMID 32992837, 2020). "Cdc42 is inhibited by StarD13 but it remains active at sites of invadopodia, where Cdc42 is required for activating nucleation promoting factors in a similar way to the spatial regulation described for RhoA and RhoC in breast cancer cells (model)." (PMID 32900380, 2020). "Altogether, these data demonstrate the pro-migratory effects of Rac and Cdc42 activation in breast cancer cells." (PMID 32992837, 2020). "Similar to studies with Rac1, inhibition of Cdc42 activation by RNAi or expression of a dominant-negative mutant reduced the ability of breast cancer cells to form lung metastatic foci." (PMID 32992837, 2020). "Several studies have implicated Rac and Cdc42 signaling in stem cell maintenance through activation of Wnt, Notch, and YAP signaling in breast cancer, NSCLC, and lymphomas." (PMID 32322580, 2020). "We demonstrated that astrocytes internalize breast cancer-derived EVs through the specific Cdc42-dependent CLIC/GEEC pathway." (PMID 32481745, 2020). "In fact, overexpression of Cdc42 in breast cancer is mainly mediated by cell surface receptors (such as epidermal growth factor receptor (EGFR)) or some oncogenes." (PMID 30754684, 2019). "The results showed that LY294002 blocked the DAPT-induced phosphorylation of AKT and reduced the DAPT-increased ratio of Cdc42-GTP/Cdc42, suggesting that DAPT activated Cdc42 through PI3K/AKT signal pathway in breast cancer cells." (PMID 31057403, 2019).
breast carcinoma (continued). "In ADM-resistant breast cancer cells, transfection of Cdc42-specific siRNA can significantly increase ADM levels and enhance its killing effects on these ADM-resistant cells." (PMID 30754684, 2019). "In our experiment, siRBPJκ didn't inhibit the effect of DAPT on activation of Cdc42 and migration when breast cancer cells treated with DAPT." (PMID 31057403, 2019). "After estradiol-17 beta treatment, breast cancer cells express higher Cdc42 levels and exhibit stronger ADM resistance, which is directly manifested by the decrease chemotherapeutic drug accumulation in cells." (PMID 30754684, 2019). "The Rho guanosine triphosphatase (GTPase) Cdc42 (Cell division control protein 42 homolog) is often upregulated by some cell surface receptors and oncogenes in breast cancer." (PMID 30754684, 2019). "One of the important ways Cdc42 affect Bcl-2 family during breast cancer is by stimulating its downstream effector PAK (both PAK1 and PAK2)." (PMID 30754684, 2019). "Substantial evidence indicates an important role for Rho GTPase Cdc42 (Cell division control protein 42 homolog), a highly conservative protein, in the progression of breast cancer." (PMID 30754684, 2019). "Cdc42 deregulation is reflected in many aspects of breast cancer processes where its role seems to be highly context dependent." (PMID 30754684, 2019). "As a result, the deregulation of Cdc42 activates pro-tumor processes, thus affecting many aspects of breast cancer." (PMID 30754684, 2019). "Nonetheless, in recent years, some Cdc42-targeted drugs are being developed in breast cancer research, aiming to inhibit Cdc42 activation in various ways." (PMID 30754684, 2019). "Previous reports have shown that CDC42 is overexpressed in various cancer tissues, including melanoma, colon cancer, and breast cancer." (PMID 30717410, 2019). "In breast cancers, some microRNAs target Cdc42 and are extensively involved in Cdc42-induced tumor processes, while many are aberrantly expressed." (PMID 30754684, 2019). "miR-206 has been demonstrated to regulate actin remodeling during breast cancer metastasis and Cdc42 is a potential target of miR-206." (PMID 30754684, 2019). "The contribution of Cdc42 to breast cancer cells is substantial, due to its critical roles in many aspects of cancer processes." (PMID 30754684, 2019). "Luckily, the antidiabetic drug metformin has been reported to inhibit breast cancer cell proliferation and migration by significantly downregulating Cdc42 expression and TNBC is sensitive to metformin." (PMID 30754684, 2019). "MBQ-167 can inhibit nearly all Cdc42-induced tumor processes in breast cancer, including cell polarity, cell cycle progression, apoptosis and metastasis." (PMID 30754684, 2019). "It is functionally required in breast cancer for the participation of Cdc42 and atypical PKC (aPKC)." (PMID 30754684, 2019). "More attention needs to be paid to the relationship between Cdc42 and breast cancer cell metastasis." (PMID 30754684, 2019). "Overexpression of Cdc42 usually leads to cancer cell migration and invasion, which are required for breast cancer spreading into the surrounding tissues and its distant metastasis." (PMID 30754684, 2019). "Treatment strategies in the future should focus on the combination of current breast cancer therapies and Cdc42-targeted therapies, with a view toward incorporating microRNAs, to reduce metastasis and diminish drug-resistance." (PMID 30754684, 2019). "MALAT1 can competitively bind to miR-1, which reduces the ability of miR-1 to inhibit Cdc42, ultimately increasing the level of Cdc42 and inducing cell migration and invasion to promote breast cancer metastasis." (PMID 30754684, 2019).
breast carcinoma (continued). "Using the orthotopic xenograft mouse model of breast cancer is critical for Cdc42-targeted drug development and for figuring out its pharmacokinetic properties and toxicity, which are important steps in demonstrating its efficacy." (PMID 30754684, 2019). "Cdc42 is an effective target for traditional Chinese medicine which has been used to inhibit breast cancer progression." (PMID 30754684, 2019). "Various regulators have been reported to target Cdc42 and influence breast cancer movement due to Cdc42 functions." (PMID 30754684, 2019). "Here, we focus on the role of Cdc42 in cell morphogenesis, proliferation, motility, angiogenesis and survival, introduce the Cdc42-targeted non-coding RNAs, as well as present current development of effective Cdc42-targeted inhibitors in breast cancer." (PMID 30754684, 2019). "The ectopic expression of miR-424, which always occurs in breast cancer patients under hyperglycemic conditions, leads to Cdc42 activation." (PMID 30754684, 2019). "P120 catenin (p120), a Src substrate that can indirectly activate Rac1 and Cdc42, acts as an obligate intermediate between ErbB2 and Rac1/Cdc42 to modulate the metastatic potential of breast cancer cells." (PMID 30754684, 2019). "Meanwhile, the scaffold protein IQGAP1 and procathepsin D can also interact with Cdc42 to enhance breast cancer cell growth and invasion in a MEK/ERK-dependent manner." (PMID 30754684, 2019). "Inhibition of Cdc42/N-WASP significantly increases the levels of cytotoxic protease granzyme B in target cells and is sufficient to transform NK cell-resistant breast cancer cells into susceptible ones." (PMID 30754684, 2019). "A recent study found that CDC42 expression correlates positively with Ki-67 expression in breast cancer." (PMID 31754397, 2019). "The Rho GTPases, Rac, and Cdc42 are key molecular switches activated by a myriad of cell surface receptors to promote breast cancer cell migration/invasion, proliferation, and survival." (PMID 31344865, 2019). "MiR-29a can precipitate cell cycle G0/G1 arrest and suppress breast cancer cell growth through direct targeting of Cdc42." (PMID 29596304, 2018). "MALAT1 can bind and inhibit miR-1; miR-1 can bind to the 3’UTR of cdc42 and decrease the expression of cdc42 to induce the migration and invasion of breast cancer cells." (PMID 29618386, 2018). "Somewhat surprisingly, it was shown that WNT5A signaling impairs breast cancer migration via activation of Cdc42." (PMID 30171384, 2018). "TNFAIP2 regulates the actin cytoskeleton, especially the membrane protrusions, to promote cell migration and invasion by regulating the activity of the small GTPase Cdc42 and Rac1 in breast cancer and nasopharyngeal carcinoma." (PMID 30145807, 2018). "Another study suggested that MALALT1, miR-1, and cdc42 are competitive endogenous RNAs (ceRNAs) in breast cancer cells." (PMID 29618386, 2018). "A distinct role for the small GTPase Cdc42 in WNT5A signaling in breast cancer cells has been demonstrated." (PMID 30171384, 2018). "Endogenous cdc42 was reported to act as a negative regulatory function on intrinsic migration or invasion of some aggressive breast cancer cells." (PMID 30504808, 2018). "Cdc42 is associated with oncogenesis non-small cell lung cancer (NSCLC), gastric cancer, breast cancer, and squamous cell carcinoma of the esophagus." (PMID 29596304, 2018). "In mammary tumor explants expressing activated Neu/ErbB-2 receptor, the Rac1/Cdc42-GAP, CdGAP, was required for TGFβ1 to induce migration and invasion." (PMID 29415466, 2018). "CDC42, a known target gene of hse-miR-608 in a human macrophage cell line U937 and a human breast cancer cell line MT-119, 59, is a small GTPase of the Rho family involved in cytoskeleton reorganization and cell migration and motility." (PMID 28860601, 2017).
breast carcinoma (continued). "In line with the finding in human breast cancer cells, the mRNA expression of CDC42 was suppressed in SK-N-SH neuroblastoma cells transfected with an hsa-miR-608 mimic (p = 3.36E-02)." (PMID 28860601, 2017). "MiR-1 binding with CDC42 (mediated by MALAT1) induced migration and invasion of breast cancer cells and CDC42 activity has been implicated in the invasive phenotype." (PMID 28589855, 2017). "Neuronal miR-326 was reported as a tumor suppressor gene in the brain, while miR-330 was reported to suppress breast cancer and colorectal cancer development by targeting CDC42." (PMID 28223918, 2017). "MALAT1 induced migration and invasion of human breast cancer cells by competitively binding miR-1 with cdc42." (PMID 28396617, 2017). "We compared CDC42 nuclear staining with the expression of other important breast cancer proteins for which IHC data were also available." (PMID 28451966, 2017). "We confirmed that simvastatin caused the translocation of the small Rho GTPases RhoA, Cdc42, and Rac1/2/3 from cell membranes to the cytosol in U251 (glioblastoma), A549 (lung adenocarcinoma) and MDA-MB-231(breast cancer)." (PMID 28344327, 2017). "MiR-330-5p has been reported to target CDC42 in human breast cancer cell line MT-1 and colorectal cancer cell SW1116." (PMID 28223918, 2017). "CDC42 is expressed at low levels in normal breast tissue and elevated in breast carcinomas, with an essential role in normal mammary development." (PMID 28451966, 2017). "We compared Cdc42 activity in different breast cancer cell lines to assess the relationship of Cdc42 activity with HER2 expression." (PMID 26783207, 2016). "Activation of the small GTPases RAC1 and CDC42 mediating cell proliferation and migration has been demonstrated in many cancers, like breast cancer, prostate cancer, lung cancer, head and neck squamous cell carcinoma." (PMID 27120794, 2016). "In HER2-positive breast cancer cells, Shp2 also mediates Cdc42 repression, and HDAC6 inhibition or co-suppression of ERK/myosin II promotes normal epithelial lumen phenotype without increasing Cdc42 activity." (PMID 26783207, 2016). "SERPINB5 is downregulated in breast cancer, and has the ability to modify the motility of breast cancer cells in vitro by inhibiting Rac1/Cdc42 activity." (PMID 27418879, 2016). "In BT474, a HER2-positive breast cancer cell line, we also found low Cdc42 activity due to Shp2-mediated repression." (PMID 26783207, 2016). "And CDC42 represents a class of Ras-related signaling molecules often deregulated in many human cancers such as testicular cancer, colorectal cancer, breast cancer, head and neck carcinoma and melanoma." (PMID 27769041, 2016). "It is well established that Rac-1 and Cdc-42 proteins, which are frequently upregulated in human cancers, including breast cancer, contribute to tumor progression and metastasis." (PMID 24675552, 2014). "MUC1 has also been implicated in cytoskeletal reorganization and cell motility through Src-CrkL-Rac1/Cdc42 signaling cascade following ICAM-1/MUC1 interaction in breast cancer cells." (PMID 24504508, 2014). "Together, these data point to the ability of WNT‐5A signaling to restrict the activity of ERK1/2 via a Cdc42‐dependent mechanism that results in impaired migration and invasion of breast cancer cells." (PMID 23727359, 2013). "On the basis of these results, we conclude that WNT‐5A impairs breast cancer cell migration and invasion by increasing the activity of Cdc42, thereby decreasing ERK1/2 activity." (PMID 23727359, 2013). "First, it drives breast cancer cell migration and invasion and second, it can be regulated by Cdc42." (PMID 23727359, 2013).
breast carcinoma (continued). "Because our results indicated that WNT‐5A comprehensively activates Cdc42 in breast cancer cells, we next performed Trans‐well migration and invasion assays with breast cancer cells in the absence or presence of WNT‐5A." (PMID 23727359, 2013). "In the next set of experiments, we performed Trans‐well migration and invasion assays to test the effect of increased activity of Cdc42 in breast cancer cells as Cdc42 is known to positively regulate cell proliferation, migration, and invasion of tumor cells." (PMID 23727359, 2013). "To explore these discrepancies, we investigated the precise role of Cdc42 in WNT‐5A‐mediated signaling in breast cancer cells." (PMID 23727359, 2013). "In all situations, increased Cdc42 activity was accompanied by decreased migration and invasion of the breast cancer cells." (PMID 23727359, 2013). "A better understanding of how Cdc42 overexpression impacts the development and progression of breast cancer will help to pinpoint when targeting Cdc42 would be most effective and will define how best to target its aberrant actions." (PMID 24074261, 2013). "Despite the fact that RhoGTPase Cdc42 is commonly associated with increased cell migration, we here show that recombinant WNT‐5A activates the Cdc42 in breast cancer cells (lines MDA‐MB468 and MDA‐MB231) in a time‐dependent manner." (PMID 23727359, 2013). "We found that basal-like breast cancer (BLBC) cells use Cdc42 to inhibit function of the redox/Fyn/c-Cbl (RFC) pathway, which normally functions to convert small increases in oxidative status into enhanced degradation of c-Cbl target proteins." (PMID 23606532, 2013). "In this study, we report that WNT‐5A‐mediated activation of Cdc42 leads to decreased breast cancer cell migration and invasion via reduced ERK1/2 and MMP‐9 activities." (PMID 23727359, 2013). "There is a recent report of an anti‐migratory function of Cdc42 in aggressive breast cancer cells, a result that supports our finding." (PMID 23727359, 2013). "In agreement, we here provide evidence that although WNT‐5A activates Cdc42, it causes a downstream decrease in ERK1/2 and MMP9 activities those results in impaired breast cancer cell migration and invasion." (PMID 23727359, 2013). "This novel mouse model will serve as an important tool to define the cellular and molecular mechanisms by which Cdc42 overexpression affects mammary tumor formation, progression, and metastasis in vivo." (PMID 24074261, 2013). "The active ezrin is also capable to recruit the guanine nucleotide exchange factor Dbl to lipid rafts and preferentially activates Cdc42, which is important for directional breast cancer cell migration." (PMID 21818323, 2011). "In breast carcinoma cells, ezrin recruits and interacts with Dbl at the plasma membrane, although in this case this results in activation of Cdc42." (PMID 20939895, 2010). "A special emphasis has already been placed on the role of Rho GTPases, and especially RhoA, Rac1 and cdc42, as ER-negative modulators in human osteosarcoma and breast cancer cells." (PMID 15642170, 2005). "Yet, a direct correlation between Rac and Cdc42 protein activity states and metastatic progression in human breast cancer remains to be demonstrated." (PMID 16280046, 2005). "To assess the potential significance of ACTR2 and CDC42 expressions in breast cancer, we generated Kaplan–Meier survival plots for relapse-free survival (RFS) and distant metastasis-free survival (DMFS) using available gene expression dataset records, spanning a period of up to 180 months." (PMID 38612766, 2024). "Additionally, when P18 was applied to MDA-MB-231 and MDA-MB-436 breast cancer cells, a slight upregulation of RhoA and Cdc42 was observed." (PMID 38927935, 2024). "Hence, we investigated the role of DOCK9 and CDC42 in elongation and intercalation of breast cancer cells." (PMID 38762624, 2024).